ARFIP1 (ARF interacting protein 1)
Description:
Plays a role in controlling biogenesis of secretory granules at the trans-Golgi network. Mechanistically, binds ARF-GTP at the neck of a growing secretory granule precursor and forms a protective scaffold. Once the granule precursor has been completely loaded, active PRKD1 phosphorylates ARFIP1 and releases it from ARFs. In turn, ARFs induce fission. Through this mechanism, ensures proper secretory granule formation at the Golgi of pancreatic beta cells.
Synonyms: HSU52521
Tractability: PROTAC: ubiquitination databases record sites on it; its protein half-life has been measured.
Gene: Protein-coding gene on chromosome 4 (152,779,096 to 152,918,463, forward strand). Ensembl gene ENSG00000164144.
Subcellular location: Golgi apparatus; Golgi apparatus, trans-Golgi network membrane
Subcellular location (Human Protein Atlas): Golgi apparatus; Vesicles; Nucleoplasm
Gene Ontology:
Molecular function: phosphatidylinositol-4-phosphate binding; protein binding; phospholipid binding; protein domain specific binding
Biological process: intracellular protein transport; negative regulation of retrograde transport, endosome to Golgi; regulation of protein secretion; regulation of Arp2/3 complex-mediated actin nucleation; intracellular protein localization
Cellular component: cytosol; Golgi apparatus; Golgi membrane; trans-Golgi network membrane
Genetic constraint (gnomAD): Loss-of-function variants: 16 observed, 27.97 expected, observed/expected ratio (o/e) 0.57, 90% interval 0.39 to 0.87. The upper end of that interval is the gene's LOEUF score, 0.87, which puts it in group 3 of 6, group 1 being the genes least tolerant of losing a copy. Missense variants: 279 observed, 372.54 expected, observed/expected ratio (o/e) 0.75, 90% interval 0.68 to 0.83. Synonymous variants: 117 observed, 134.81 expected, observed/expected ratio (o/e) 0.87, 90% interval 0.75 to 1.01.
Homologues: Orthologues: chimpanzee ARFIP1 (100% identical), macaque ARFIP1 (99% identical), dog ARFIP1 (98% identical), guinea pig ARFIP1 (97% identical), pig ARFIP1 (96% identical), mouse Arfip1 (92% identical), rat Arfip1 (92% identical), tropical clawed frog arfip1 (82% identical), rabbit ARFIP1 (80% identical), zebrafish arfip1 (67% identical), Drosophila melanogaster Arfip (43% identical), Caenorhabditis elegans F54C8.7 (27% identical). Paralogues in human: ARFIP2 (53% identical), PICK1 (21% identical).
Diseases named in the same sentence as ARFIP1 in open-access papers:
ARFIP1 is named in the same sentence as 4 diseases in open-access papers, as found by Europe PMC text mining. Sharing a sentence is not in itself a finding about the gene and the disease. The quoted sentences say what the papers report.
mouth ulcers (1 paper, 2023). "The proteins encoded by eight genes (PMEL, ARFIP1, FAM213A, GLUL, CADM2, FAIM3, RIPK2, and DECR1) have only one SNP instrumental variable and have a association with mouth ulcers using the Wald ratio method." (PMID 37369724, 2023).
ARFIP1 also shares sentences with these, for which no sentence is quoted: cancer (2 papers); dwarfism (1); tumor (1).